TLE1 (TLE family member 1, transcriptional corepressor)
Diseases named in the same sentence as TLE1 in open-access papers (continued):
Sharing a sentence is not in itself a finding about the gene and the disease.
glioma (1 paper, 2018). A benign or malignant brain and spinal cord tumor that arises from glial cells (astrocytes, oligodendrocytes, ependymal cells).
glomus tumour (1 paper, 2025). "Subsequently, no studies have evaluated the TLE-1 status of glomus tumours." (PMID 41561522, 2025).
inflammatory bowel disease (1 paper, 2022). A spectrum of small and large bowel inflammatory diseases of unknown etiology. "For example, TLE1 was reported to interact with NOD2 and thus inhibit NF-κB signaling, and TLE1 gene mutation or reduced TLE1 expression was found to be associated with the pathogenesis of inflammatory bowel disease and hepatic ischemia/reperfusion injury." (PMID 36438567, 2022).
Miscarriage (1 paper, 2020). A pregnancy that ends at a stage in which the fetus is incapable of surviving on its own, defined as the spontaneous loss of a fetus before the 22th week of pregnancy. "Mapping of potential candidate genes at associated loci identified several genes (FGF9, TLE1, TLE4, E2F8, SIK1) with a plausible biological role in placental biology and miscarriage etiopathogenesis." (PMID 33239672, 2020).
salivary gland neoplasms (1 paper, 2018). Tumors of the SALIVARY GLANDS. "Further studies are warranted to confirm the utility of TLE1 immunohistochemistry in salivary gland tumors." (PMID 30053869, 2018).
spindle cell tumors (1 paper, 2020). "Although IHC for bcl-2, HHF35, and TLE-1 is useful for the diagnosis of spindle cell tumors, the diagnostic ability of IHC to detect SS is limited." (PMID 32691176, 2020).
T-cell acute lymphoblastic leukemia (1 paper, 2021). Acute lymphoblastic leukemia of T-cell origin. "The aim of this study was to address the prognostic value of TLE1 gene expression in patients with T cell acute lymphoblastic leukemia." (PMID 34048198, 2021).
tumor (75 papers, 2010 to 2026). "Overall, SS18 (SYT) gene rearrangement and TLE1 expression are crucial diagnostic markers for differentiating PCSS from other neoplasms." (PMID 41982499, 2026). "TLE1 deficiency also resulted in lung hypoplasia, decreased overall survival, and enhanced transplanted tumor growth." (PMID 34048198, 2021). "The other common region between UKB and GWAS Catalog is located on chromosome 9 and spans the TLE1 gene encoding a transcriptional corepressor that is involved in tumor progression, cell growth, and inflammation processes." (PMID 32403311, 2020). "TLE1 expression was also associated with prognostic clinicopathological parameters, including gender, American Joint Committee on Cancer Stage, and tumor depth." (PMID 27852056, 2017). "In acute myeloid lymphoma, loss of TLE1 or TLE4 increases cell proliferation suggesting that under some conditions TLE proteins may act as tumor suppressors." (PMID 30719233, 2019). "Additionally, TLE1 deficiency resulted in enhanced tumor growth." (PMID 27852056, 2017). "In our case, the tumor was of monophasic histology and was diffusely positive for TLE1, Bcl2, and CD56 immunostaining." (PMID 40747128, 2025). "Tumor cells were immunoreactive with a 4+ grade for the TLE1 marker in our case, along with a 3+ grade for CD99 establishing a proper diagnosis for SS." (PMID 38410005, 2024). "In vitro experiments showed that TLE1 promotes tumor proliferation and migration and inhibits apoptosis." (PMID 37481739, 2023). "And TLE1 plays a role in participating in the immune inflammatory response, suppressing apoptosis of lost nests, and suppressing tumor activity but also acting as an oncogene in some tumors." (PMID 37032832, 2023). "MAPK signaling leads to TLE1 phosphorylation and inhibits TLE1 suppressive activity by translocating it from the nucleus to the cytoplasm in tumor cell lines." (PMID 36438567, 2022). "Immunohistochemistry showed that the tumor cells were diffusely positive for TLE-1 and vimentin and focally positive for epithelial membrane antigen, AE1/3, Cam5.2, SATB2, and CD34 (all in less than 10% tumor cells)." (PMID 35125107, 2022). "By IHC, the tumor cells were diffusely positive for TLE-1 and vimentin and focally positive for epithelial membrane antigen, AE1/3, Cam5.2, SATB2, and CD34 (all in less than 10% tumor cells)." (PMID 35125107, 2022). "In contrast, depletion of TLE1 in leukemic cells enhanced tumor growth, indicating epigenetic inactivation of TLE1 promoted the development of hematological malignancies by disrupting cell differentiation and growth-suppressive pathways." (PMID 34048198, 2021). "TLE1 expression in tumor and para-tumor tissues was evaluated by tissue microarray-based immunohistochemistry using a semiquantitative method (H-score) in 262 patients with radical PDAC resection." (PMID 32432037, 2020). "In this study, despite higher TLE1 expression in tumor tissues than in para-tumor tissues, both in vitro experiments and clinicopathological and prognostic analyses revealed a tumor-suppressing role for TLE1 in PDAC." (PMID 32432037, 2020). "Immunohistochemistry revealed that TLE1 was specifically expressed in the nucleus and at higher levels in tumor tissues compared with para-tumor tissues." (PMID 32432037, 2020). "TLE1 overexpression was correlated with benign tumor behaviors and a better prognosis in PDAC patients." (PMID 32432037, 2020). "The tumour consisted of spindle cells positive for TLE1 and CD99 and for the fusion transcript SS18-SSX determined in routine diagnosis." (PMID 30745580, 2019).
tumor (continued). "Conversely, depletion of TLE1 in unmethylated cells by shRNA enhanced tumor growth, indicating epigenetic inactivation of TLE1 promoted the development of hematologic malignancies by disrupting cell differentiation and growth-suppressive pathways." (PMID 27852056, 2017). "The TLE1/control shRNA expressing cells showed increased primary tumor growth kinetics as compared to control/control shRNA cells." (PMID 29069783, 2017). "Formalin-fixed paraffin embedded (FFPE) patient-derived synovial sarcoma tumor samples were used to detect SS18-SSX/TLE1 co-localization in human tumor tissue samples." (PMID 27120803, 2016). "Individually silencing sFRP4, GSK3β, or TLE1 increased the tumour sphere formation and enhanced the TOP flash/FOP flash activity of antagomir-942 cells." (PMID 25844602, 2015). "The tumor cells demonstrated diffuse intranuclear TLE-1 with focal EMA and cytokeratin positivity and DOG-1 negativity." (PMID 22966471, 2012). "Immunohistochemically, tumor cells express TLE1, EMA, CK19, and some cases could express S-100, CD99, and Bcl-2." (PMID 40826697, 2025). "The current case showed diffuse TLE-1 positivity in all tumour cells." (PMID 41561522, 2025). "By IHC, the tumor cells were positive for Vimentin, TLE1, and CD10." (PMID 39469368, 2024). "Microscopically, the tumor showed the proliferation of monotonous spindle cells with immunohistochemical expression of epithelial membrane antigen, B-cell leukemia/lymphoma 2, and transducin-like enhancer of split 1 (TLE1)." (PMID 35029897, 2022). "TLE1 was weakly positive for the tumor cell nuclei and INI1 was retained." (PMID 32957984, 2020). "Therefore, these questions and the contradiction between the difference in TLE1 expression between tumor and para-tumor tissues and the favorable prognosis of patients with higher tumor TLE1 expression warrant further study." (PMID 32432037, 2020). "Moreover, TLE1 has been regarded as a prognostic biomarker in several tumor types and is also related to several clinicopathological features of patients." (PMID 32432037, 2020). "Using RNA sequencing and bioinformatics, we identified 16 genes that are involved in various cell biological processes that may be regulated by TLE1 expression and then influence tumor progression." (PMID 32432037, 2020). "Positive TLE1 staining was observed in the nuclei of both tumor and para-tumor tissues." (PMID 32432037, 2020). "Inhibition of TLE1 function may prevent cancer cell self-renewal resulting in decreased tumor burden." (PMID 27852056, 2017). "The TLE1 gene functions as a tumor suppressor in myeloid leukemia." (PMID 27852056, 2017). "However, expression of TLE family members (e.g. TLE3, an analog of TLE1) correlated with the degree of tumor differentiation." (PMID 27852056, 2017). "There is no satisfactory differential diagnostic marker because S-100, epithelial markers, TLE1 and SOX 10 could be positive in both tumours." (PMID 26112006, 2015). "Therefore, TLE1 may have tumor suppressive roles in T-ALL development, consistent with the observation that low TLE1 expression is associated with poorer survival in T-ALL patients." (PMID 36438567, 2022). "Furthermore, in vitro cell biology experiments showed that TLE1 overexpression not only impaired cell migration and invasion but also inhibited cell proliferation by impeding G0/G1 transition, which consolidated the tumor-suppressing role of TLE1 in PDAC." (PMID 32432037, 2020). "However, the reason why TLE1 expression was higher in tumor tissues compared with para-tumor tissues in our study still remains unclear." (PMID 32432037, 2020). "Specifically, these genes regulated by TLE1 are involved in signaling pathways such as naive CD8+ T cells, calcineurin-regulated NFAT-dependent transcription in lymphocytes, and EMT, which indicated that TLE1 may participate in biological processes such as immune regulation and tumor metastasis." (PMID 32432037, 2020).
tumor (continued). "Having a dual role in potentiating EMT and anoikis resistance as described here, the ZEB1/TLE1-mediated transcriptional silencing of the tumor suppressive E-cadherin expression represents an important molecular event that may impact the initiation and progression of lung malignancy." (PMID 29069783, 2017). "In our patient's case, the tumor consisted of small round cells and was CD99+, BCOR+, FLI1+, TLE1−, and NKX2.2−." (PMID 40115314, 2025). "Immunohistochemically, the tumor was positive for CD10, CD34, TLE1, estrogen, and progesterone receptors." (PMID 40878061, 2025). "Tumor cells were reactive to SMA, cluster of differentiation 34 (CD34) (focally), transducin-like enhancer of split-1 (TLE-1) (focally), and cyclin D1, with nuclear staining of beta-catenin, while it was not reactive to cytokeratins." (PMID 41246587, 2025). "In this model, logistic regression analyses demonstrated that clinical parameters (age, gender, and tumor stage) and core molecules (SLC2A1, TLE1, FAM83A, HMGA2, FBXO44, and MTRNR2L12) contributed differently to LUAD scores at different stages." (PMID 38338834, 2024). "In our study, almost all neoplasms were positive for BCL2, CD99, CD56, FLI1, TLE1, MUC4, and PDGFR alpha." (PMID 39062853, 2024). "Immunohistochemistry results showed positivity for TLE1, EMA, BCL-2, CKH, CK18, and Kiel-67 (in 46% of cells) in some regions of tumor cells; and negativity for Desmin, CD34, S-100, and CD117 in tumor cells." (PMID 38013382, 2023). "The tumor stained positive for pancytokeratin, AE1/AE3, epithelial membrane antigen (EMA), TLE-1, CD99, and BCL-2." (PMID 38188535, 2023). "Analysis from the first sample showed the tumor cells were diffusely positive for Lu-5, P40, CD56, and vimentin, focally positive for transducin-like enhancer of split-1 (TLE1), and rarely positive for synaptophysin and DOG1." (PMID 35481321, 2022). "On the basis of the role of TLE1 in tumor metastasis ability, we further explored the effects of TLE1 on epithelial–mesenchymal transition (EMT), which plays an essential role in tumor cell migration and invasion." (PMID 32432037, 2020). "The IHC staining was positive for CD99 and FLI-1 (in >50% of tumor cells) and negative for AE1/AE3, INI-1 loss, WT1, desmin, myogenin, BCOR, TLE-1, CD45CLA, and synaptophysin." (PMID 41230381, 2026). "Notably, LDHA, SHC1, and EPHX1 exhibited heightened expression levels in tumor tissues, while MYO6 and TLE1 displayed diminished expression compared to normal tissues." (PMID 37965333, 2023). "The tumor was positive for CD117, Vim, CD56 and NSE and showed focal expression of desmin but was negative for myogenin, S-100, SYN, INSM1, CD34, STAT6, INI-1, Brachyury, ERG, TLE1, AE1/AE3, WT-1, CD99 and SMA." (PMID 35488288, 2022). "Immunohistochemically, the tumor cells were positive for CD117, vimentin, CD56 and NSE and focally expressed desmin; the cells were negative for myogenin, S-100, SYN, INSM1, CD34, STAT6, INI-1, Brachyury, ERG, TLE1, AE1/AE3, WT-1, CD99 and SMA." (PMID 35488288, 2022). "In addition, the immunohistochemical results showed the altered staining patterns of BCOR, bcl2, CyclinD1, TLE1, AR, SMA, CD117, STAB2, CD56, and CD99 in tumor tissues after chemotherapy." (PMID 35568949, 2022). "In our present study, high TLE1 expression was significantly associated with benign tumor behavior, and absent vascular invasion though TLE1 expression in tumor tissues was higher than in para-tumor tissues." (PMID 32432037, 2020).
tumor (continued). "TLE1 expression was also a marginal prognostic indicator in the subgroups female, age > 60 years, non-head tumor location, and G3–G4 tumor grade in the multivariate analysis (0.05 < P < 0.1)." (PMID 32432037, 2020). "Further, immunostaining of tumor cells was positive for TLE1 and BCOR, and negative for cytokeratin (AE1/AE3), Desmin, CD45, S100, CD31, HMB45, and SATB2." (PMID 31702654, 2019). "Immunostaining revealed that the tumor cells were positive for TLE1 and BCOR, and negative for cytokeratin (AE1/AE3), Desmin, CD45, S100, CD31, HMB45, and SATB2." (PMID 31702654, 2019). "BCA showed positive TLE1 expression in the luminal cells of glandular structures, regardless of the tumor growth patterns." (PMID 30053869, 2018). "The tumor however was double positive for CD99 and TLE1 which made it difficult to discriminate it from the myxoid variant of SS based on histopathological examination and immunophenotype alone, and genetic analysis for SYT gene rearrangement was required to reach a definitive diagnosis." (PMID 30410809, 2018). "TLE1 and TLE4 were considered as tumor suppressors in hematological malignancy." (PMID 26701208, 2016). "In particular, the over-expression of TLE1 appears to be a reliable marker to discriminate SS from other types of STS, independently from the type of SSX fusion and the degree of tumor differentiation, although a study showed TLE1 to be expressed also in other non-synovial STS." (PMID 23158439, 2012). "Previous studies showed that the mechanisms of TLE1 in tumor progression regulation may involve its negative modulation of Wnt/β-catenin and NF-κB pathways, which have been confirmed as core signaling pathways for tumorigenesis in PDAC." (PMID 32432037, 2020). "Therefore, high TLE1 expression in PDAC tissues may relate to CD8+ T cell infiltration, which also has a tumor-suppressive role." (PMID 32432037, 2020). "INI-1 was retained in the tumor cells, and WT1, desmin, myogenin, BCOR, TLE-1, CD45CLA, and synaptophysin were all negative (not shown)." (PMID 41230381, 2026). "The tumor was positive for CD99, SATB2, TLE1, cyclin D1, and focal FLI1, while negative for EMA, S100, desmin, calponin, and SOX10." (PMID 41869091, 2026). "Immunohistochemical (IHC) staining revealed that the tumor cells were diffusely positive for SOX11 but negative for SATB2, CD56, S100, and TLE1." (PMID 40791569, 2025). "The tumor cells expressed SATB2, Bcl-2, TLE1, SMARCB1, but not CK, EMA, CD34, SMA, Desmin, S-100, CD99, STAT6, MyoD1, Myogenin, and Ki-67 LI is about 10%." (PMID 37361584, 2023). "Desmin, SMA, S100, CD31, Caldesmon, TLE-1, WT-1 and SS18 were negative in the tumor." (PMID 40831926, 2025). "Histopathology revealed a cellular tumor comprising tightly packed round to fusiform cells arranged around blood vessels with intervening thick collagen, positive for CD99, vimentin, BCL2, CD34, and STAT6 and negative for EMA, CK AE1/AE3, S100, TLE1, and SMA." (PMID 38606238, 2024). "In the IHC study, tumor cells showed positivity for CD99, EMA, vimentin, and TLE1, while they were negative for NKX2.2, WT1, BCOR, PDGFA, cytokeratins, muscle markers (smooth muscle actin, desmin, caldesmon, MyoD1, and myogenin), and melanocytic markers (HMB45, SOX10, and S100)." (PMID 38339014, 2024).
tumor (continued). "However, in the multivariate analysis, TLE1 expression remained significantly different in only four subgroups: age ≤ 60 years, non-diabetic, elevated CA19-9, and small tumor size (≤ 4 cm) (P < 0.05)." (PMID 32432037, 2020). "Additionally, the tumor was negative for most immunohistochemical markers (CKAE1/AE3, p63, CD23, CD21, MUC4, NUT, CDK4, Pan-TRK, STAT6, SS18, MDM2, Desmin, S100, ERG, TLE1, Fli) and showed only weak and most probably unspecific expression of CD99, CD56, and CD34." (PMID 39519042, 2024). "(Immunohistochemical stains showed that the tumor cells were positive for desmin and TFE3, while negative for pancytokeratin, CAM5.2, EMA, chromogranin, synaptophysin, NSE, CD45, SMA, HHF35, myogenin, CD117, DOG1, MUC4, S100, SOX10, HMB45, Melan-A, CD31, ERG, TLE1, STAT6, and Cathepsin-K)." (PMID 35001360, 2022).